ENSG00000206913
Synonyms: LOC124902824
Gene: Small nucleolar RNA gene on chromosome 11 (74,252,414 to 74,252,552, reverse strand). Ensembl gene ENSG00000206913.
Gene Ontology:
Biological process: RNA processing
Cellular component: nucleolus
Homologues: Paralogues in human: SNORA7A (87% identical), SNORA7B (86% identical).